NF2 (NF2, moesin-ezrin-radixin like (MERLIN) tumor suppressor)
Diseases named in the same sentence as NF2 in open-access papers (continued):
Sharing a sentence is not in itself a finding about the gene and the disease.
schwannoma (continued). "Identifying the oxidized proteins, and the critical residues in those proteins involved in the regulation of energy metabolism in NF2 schwannomas will provide exceptional new targets for the development of therapies directed specifically to tumor cells." (PMID 31171721, 2019). "The cohort included 115 schwannomas (11%) from NF2-patients and 37 tumors (4%) that received radiotherapy prior to resection." (PMID 31291992, 2019). "Individuals with NF2 develop multiple benign tumors including schwannomas, meningiomas, and ependymomas throughout their lifetime." (PMID 31171721, 2019). "Here we show an exploratory clinical study of VEGFRs peptide vaccine in seven patients with progressive NF2-derived schwannomas." (PMID 31848332, 2019). "Expression of NOS regardless of the isoform was associated with production of peroxynitrite, as evidenced by increased tyrosine nitration, which was beneficial for NF2 schwannoma cell survival." (PMID 31171721, 2019). "At this anatomic site, mice with a conditional-knockout of Nf2 (Nf2f/f;PostnCre+) exhibit Schwann cell hyperplasia or frank schwannoma formation by 6 months of age." (PMID 29416648, 2018). "GSK2126458, Panobinostat, and CUDC-907 were evaluated in a genetically-engineered mouse (GEM) model of NF2, PostnCre; Nf2floxflox, that develops schwannoma of the dorsal root ganglia (DRG) and cranial nerves." (PMID 29897904, 2018). "In NF2, tumors usually grow bilaterally, and compared to sporadic schwannomas, they grow faster, have a higher recurrence rate, and are much more adherent to the cranial nerves and the brainstem." (PMID 29515781, 2018). "Since day 3 after seeding the percentage of EdU-positive cells was significantly higher in schwannoma cells with NF2 shRNAs than in those with nonsense controls." (PMID 28710469, 2017). "In an NF2-derived human schwannoma cell line (HEI-193) and in human primary VS cells from 3 different tumors, αv integrin was overexpressed on the cell surface as determined by immunofluorescence staining." (PMID 29018206, 2017). "To mimic the growth promoting effects by the second hit, we performed lentivirus-mediated NF2 knockdown in the ‘one-hit’ schwannoma cultures." (PMID 28710469, 2017). "Following merlin depletion, HSC increased the levels of phosphorylated SRC and PDGFRα/β, in agreement with studies in primary human NF2 schwannoma cells." (PMID 28427224, 2017). "In most schwannomas from patients harbouring LZTR1 germline mutations, the chromosome 22 is retained that harbours the germline LZTR1 mutation and an NF2 allele with a somatically acquired tumour-specific mutation." (PMID 27921248, 2017). "PEATE e cVEMP, quando utilizadas em combinação, podem ser úteis na identificação de condições neuro-otológicas como schwannoma vestibular e tumores bilaterais em NF2." (PMID 27174775, 2017). "Although the exact molecular pathogenetic mechanisms in these schwannomas remain to be elucidated, a 4-hit/3-step mechanism involving SMARCB1 and NF2 genes seems to underlie development of these benign tumors in schwannomatosis patients." (PMID 28824165, 2017). "The chromosome 22 carrying the mutant SMARCB1 allele was retained in the pRCC1 and in schwannomas from this patient, whereas the wild-type SMARCB1 allele and one NF2 copy were lost by deletion." (PMID 27921248, 2017). "Future in vivo studies addressing ponatinib alone or in combination as an effective therapy for schwannomas in NF2 mouse models are warranted." (PMID 28427224, 2017). "Consistently, 40 % of all schwannomas were found to have at least one intact wild-type copy of the Nf2 gene remaining." (PMID 27236462, 2016). "NF2 disease can often mean lifelong deafness, as schwannomas predominantly appear at the vestibulocochlear nerves (vestibular schwannoma)." (PMID 27236462, 2016). "We report a series of patients with NF2 harboring schwannoma-neurofibroma hybrid nerve sheath tumors." (PMID 26709712, 2016).
schwannoma (continued). "To identify the target/s of crizotnib we employed activity-based protein profiling (ABPP), leading to identification of FAK1 (PTK2) as the relevant target of crizotinib inhibition in NF2-null schwannoma cells." (PMID 27363027, 2016). "In our study, there was a 26% incidence of schwannoma/neurofibroma hybrid tumors in patients diagnosed with NF2 that underwent surgical resection." (PMID 26709712, 2016). "In summary, our studies identify an FDA approved drug, crizotinib, which shows in vitro and in vivo efficacy against NF2-null schwannomas." (PMID 27363027, 2016). "The schwannoma/neurofibroma hybrid tumor should be included in the differential diagnosis of nerve sheath tumors in patients with NF2." (PMID 26709712, 2016). "It has been reported that patients with NF2 have developed schwannoma in the nasal cavity and paranasal sinuses." (PMID 27882056, 2016). "To assess if crizotinib can inhibit tumor growth in vivo, we employed an orthotopic model of NF2 that recapitulates the tumor microenvironment of schwannomas, by injection of luciferase-tagged NF2-null SC4 cells into a myelinated nerve." (PMID 27363027, 2016). "Like tumorlets in sural nerve biopsies of NF2 patients, the disordered cell clusters presented an Antoni A growth pattern, the primary growth pattern of schwannoma in mice." (PMID 27236462, 2016). "Although sporadic hybrid schwannoma/neurofibroma tumors have been described, schwannoma/neurofibroma hybrid tumors in the setting of NF2 have rarely been reported in the literature, and their pathology has not been fully described." (PMID 26709712, 2016). "SNP-array analysis revealed the presence of the same deletion breakpoint in both schwannomas, indicating that this alteration was actually the first NF2 inactivating hit." (PMID 25739810, 2015). "The four-hit, three-step model of tumorigenesis of schwannomas from SMARCB1 positive patients forced us to perform an exhaustive mutational analysis of both SMARCB1 and NF2 genes, since they are somatically inactivated in both alleles." (PMID 25739810, 2015). "A minimum of 25-33% of NF2 sporadic cases are mosaic, and a few of them develop multiple schwannomas confined to one body segment (see for instance)." (PMID 25739810, 2015). "The results highlight the importance of undertaking a mutational analysis for NF2 and SMARCB1 in at least 2 schwannomas in sporadic patients with a Schwannomatosis phenotype before concluding a clinical diagnostics." (PMID 25739810, 2015). "This analysis is challenged by the fact that schwannomas in both conditions bear a somatic double inactivation of the NF2 gene." (PMID 25739810, 2015). "Originally, schwannomas were held to primarily account for observable neuropathic symptoms developing in the course of NF2." (PMID 25012216, 2014). "Differences in gene expression between schwannomas or between schwannoma cells from NF2 patients and normal human primary schwann cells previously examined do not confer age impact." (PMID 24980480, 2014). "As concerns patients with NF2, schwannomas of the intestinal tract are a possible complication, whereas there are no data about coexistence with GEP NET and/or MEN1 syndrome." (PMID 24961548, 2014). "In order to validate the results in our cellular model, we measured SIRT2 and acetyl-α-tubulin levels in a human NF2 cell line created by immortalization of schwannoma cells from a NF2 patient with the E6 and E7 genes of the papillomavirus." (PMID 24259290, 2013). "In a pilot high-throughput screen of the Library of Pharmacologically Active Compounds, we assayed for compounds capable of reducing viability of mouse Schwann cells (MSC) with Nf2 inactivation as a cellular model for human NF2 schwannomas." (PMID 24259290, 2013). "It has been shown that mitotic recombination plays a role in the occurrence of LOH, even though the rate of mitotic recombination is relatively low in sporadic VS compared to NF2-related schwannomas." (PMID 22295085, 2012).
schwannoma (continued). "The analysis with both markers demonstrated that 43.75% of schwannomas exhibited LOH of the NF2 gene." (PMID 22911524, 2012). "The main reason why we propose studying NF2 gene in schwannomas is because there are still many unsolved and inadequately explained issues regarding the full genetic profile of human schwannomas." (PMID 22911524, 2012). "In this preclinical study, the human NF2-null schwannoma cell line HEI-193 subjected to nilotinib inhibition demonstrated decreased viability, proliferation and anchorage-independent growth, and increased apoptosis." (PMID 22745749, 2012). "In rat schwannoma cells, NF2 expression transiently reduces cell attachment to Fn, with levels returning to normal after 3 h." (PMID 23170136, 2012). "We have already mentioned that gross deletions of the NF2 gene are frequent events in the molecular pathology of sporadic schwannoma." (PMID 22911524, 2012). "The main differential diagnosis of NF2 is schwannomatosis and some patients with multiple non cranial schwannomas turn out to have mosaic NF2." (PMID 19545378, 2009). "The standard approach of mutational analysis and Loss of Constitutional Heterozygosity (LOH) on tumours will detect involvement of NF2 in about 80–90% of schwannomas, but both copies can only be confirmed as affected in about 50–60% of cases." (PMID 19545378, 2009). "In most cases, while schwannoma is sporadically manifested as a single benign neoplasm, the presence of multiple schwannomas in one patient is usually indicative of neurofibromatosis 2 (NF-2)." (PMID 19574706, 2009). "It is very uncommon to have to remove a schwannoma growing on a cranial nerve other than the eighth because these tumours appear to have a much slower growth pattern than NF2 VS." (PMID 19545378, 2009). "There is no approved drug therapy for schwannomas associated with NF2-related schwannomatosis (NF2-SWN)." (PMID 41898501, 2026). "In our case, whole-exome sequencing confirmed the absence of NF2 mutations, supporting the diagnosis of a sporadic schwannoma." (PMID 40672023, 2025). "Further, all 17 schwannomas also exhibited somatic intragenic NF2 PVs." (PMID 40794298, 2025). "Smarcb1 loss and biallelic Nf2 inactivation at later stages of Schwann cell development (starting at E13.5) lead to benign schwannomas but not rhabdoid tumours." (PMID 40794298, 2025). "Additional inactivation of the NF2 gene is also necessary for schwannoma development." (PMID 40794298, 2025). "Nevertheless, it is plausible that the events which drive schwannoma growth differ depending upon the presence or absence of a germline PV in one of the three schwannoma predisposition genes (NF2, SMARCB1 and LZTR1)." (PMID 40794298, 2025). "Histological analysis of the DRG of an NF2 patient showed that they were massively infiltrated by schwannoma tissue, with the regular architecture of a more central, nerve fibre-rich area and a more peripheral, cell body-rich area completely disrupted, indicating a remodelling of the DRG." (PMID 40437318, 2025). "However, the vast majority of previous studies that addressed the genomic, gene expression and DNA methylation profiles of schwannomas have been focussed on sporadic schwannomas or those of patients with NF2-related SWN." (PMID 40794298, 2025). "Schwannomas of the GIT are mostly benign origin, but under certain conditions they also have malignant potential, e.g. in some genetic diseases such as neurofibromatosis (type 1 + 2), when the tumor suppressor genes NF1 and NF2 are mutated." (PMID 40678162, 2025). "Group 3 histological schwannomas were associated with recurrent CNVs deleting chromosome 22q (including the NF2 locus) but no other CNVs." (PMID 38216572, 2024). "We found Hsp90 endogenously nitrated in schwannoma cells and in resected tumors from NF2-SWN patients, suggesting that in tumor cells, nitrated Hsp90 may play a proliferative function." (PMID 38945076, 2024).
schwannoma (continued). "Bevacizumab has therefore become a widespread treatment for NF2-related schwannomas." (PMID 38672561, 2024). "Additionally, schwannomas and neurofibromas are tightly linked with genetic conditions such as neurofibromatosis type 1 (NF1) and NF2, with schwannomatosis emerging as a separate syndrome associated with SMARCB1 mutations." (PMID 39001422, 2024). "While the recent success of TEAD inhibitors in other NF2-altered cancers is exciting, the slow-growing, benign nature of schwannomas may make them difficult to target with any monotherapy." (PMID 39083549, 2024). "Schwannomas from NF2 patients were described as exhibiting PAK activation due to merlin loss." (PMID 38336988, 2024). "TEAD palmitoylation inhibitors like those developed by Vivace Therapeutics were first tested in NF2-deficient mesothelioma and have also been effective in reducing Schwannoma tumor size in vivo without side effects." (PMID 39083549, 2024). "A thorough understanding of the complex and intersecting molecular pathways involved could identify new targets and inhibitors to slow NF2 schwannoma disease progression." (PMID 38336988, 2024). "In line with the two-hit model of tumour suppression, the biallelic mutation of NF2 leads to the development of neurofibromatosis type II (NF2), a tumourigenic genetic disease characterised by bilateral schwannoma formation along the vestibulocochlear cranial nerve." (PMID 38338806, 2024). "The etiology of Schwannoma is unknown, but in some literature, Schwannoma occurs due to a defect in the NF2 gene." (PMID 38615463, 2024). "Individuals with pathogenic changes in the NF2 gene, which encodes merlin, a cytoskeletal linker protein that regulates Hippo–YAP signaling, can develop benign nerve sheath tumors called schwannomas anywhere in the body." (PMID 38353122, 2024). "Molecular characterization using focused next-generation sequencing did not identify SMARCB1 or NF2 mutations, alterations previously associated to schwannoma at other anatomical sites." (PMID 37535242, 2023). "Finally, we performed an analogous analysis in SC4 cells, an immortalized mouse schwannoma NF2−/− cell line, that has been used to study NF2 proliferation effects." (PMID 37280085, 2023). "Furthermore, these tumors clustered together with SOX10-mutant sporadic schwannomas which we previously found are epigenetically distinct from NF2-mutant schwannomas." (PMID 37821623, 2023). "We found that Nf2−/− schwannoma cells readily take up EVs in an EIPA-sensitive manner." (PMID 36944680, 2023). "It is a disease process with a predisposition to schwannomas in the absence of bilateral vestibular schwannomas, which differentiates it from neurofibromatosis 2 (NF2)." (PMID 35475061, 2022). "In our previous studies, primary schwannoma cells (JEI-001) were obtained from a 41-year-old vestibular schwannoma patient, cultured, and immortalized using lentivirus-mediated infection, and JEI-001 contains an Exon 5 mutation of the NF2 gene (c.515delG)." (PMID 35359340, 2022). "The orthotopic schwannoma model used here is a validated pre-clinical model of NF2 schwannomas." (PMID 35875610, 2022). "VEGF expression in NF2-related schwannomas has been reported." (PMID 33572546, 2021). "Our genetic analysis revealed that the tumor did not have any somatic variants pertinent to schwannoma, such as in NF2 and 22q loss." (PMID 34407809, 2021). "Schwannomas in NF2 often occur with other skull base tumors." (PMID 36285231, 2021). "HA levels were elevated in NF2-VS and correlated with the proliferation rate of schwannoma cells." (PMID 34646772, 2021). "In the case of LZTR1, a single-nucleotide pathogenic variant as a second hit would not lead to loss of NF2 on the same allele and would almost certainly not advance schwannoma formation." (PMID 33879870, 2021). "Sporadic, NF2-associated, and schwannomatosis-associated schwannomas are indistinguishable aside from the molecular diagnosis." (PMID 33669386, 2021).
schwannoma (continued). "Schwannoma cells increase their self-reproductive potential by secreting HA under the innate condition, suggesting that elevated HA in the CSF of patients with NF2-VS may be used as an indicator of tumor growth." (PMID 34646772, 2021). "Furthermore, Cre-mediated excision of the NF2 gene under the control of the periostin promoter element in mice results in multiple discrete schwannoma tumor nodules along the eighth cranial nerve." (PMID 31161239, 2020). "Therefore, it is essential to understand how schwannoma tumorigenesis works on a molecular level, thus unraveling the mechanisms of the tumor suppressive functions of the nf2 gene product merlin." (PMID 32616891, 2020). "In an in vivo Nf2 knockout model of schwannoma formation, mice bred to have a combined heterozygous Nf2 deletion in both Schwann cells and neurons (P0-Cre;Nefh-Cre;Nf2fl/+) almost uniformly developed Sciatic nerve schwannomas following crush injury at 8 months of age." (PMID 32642684, 2020). "Schwannomas comprise the majority of cutaneous tumors in NF2." (PMID 32591014, 2020). "One reason proposed for the development of schwannomas in this mouse model is a failure of Schwann cell re-differentiation into myelinating cells, due to absent signals from nf2-deficient neurons." (PMID 32616891, 2020). "We observed that NF2 was highly expressed in mouse schwannoma." (PMID 32960816, 2020). "Patients with NF2-associated VS not only get symptomatic earlier but also suffer additional benign nervous system tumors (e.g., meningiomas, non-VS schwannomas, and ependymomas) and/or are associated with other manifestations such as vascular disease." (PMID 31936793, 2020). "All NF1 patients had neurofibromas, all NF2 and schwannomatosis patients had schwannomas." (PMID 32506255, 2020). "Schwannomas occur mostly in patients with NF2, schwannomatosis or as solitary lesions." (PMID 32506255, 2020). "To exclude this possibility, we performed immunostaining of NF2 in mouse schwannoma." (PMID 32960816, 2020). "Conversely, overexpression of NF2 in HEI 193 schwannoma cell line inhibited PDGFR/PDGF activity." (PMID 32299434, 2020). "If a peripheral schwannoma is removed in a child or adolescent, the existence of an underlying NF2 has to be ruled out actively by performing MRIs of the head and the spine." (PMID 32506255, 2020). "The NF1 mechanism is distinct from that in NF2 involving the mutation of NF2, which encodes the ezrin-radixin related protein, merlin, resulting in the development of true schwannomas rather than cNF or pNFs." (PMID 31107888, 2019). "Moreover, several tumor cell types exhibit low levels of MnSOD (50, –, 52), further supporting the role of peroxynitrite in the redox signaling processes regulating NF2 schwannoma cell survival and growth." (PMID 31171721, 2019). "Here we show that peroxynitrite is necessary for NF2 schwannoma cell survival." (PMID 31171721, 2019). "In this study, low PD-L1 expression was observed in the schwannomas of most NF2 patients." (PMID 31848332, 2019). "A significant decrease in cell survival was also observed in human MD-Schwann cells after 96 h of treatment with l-NAME, FeTCPP, and urate compared with human WT-Schwann cells, suggesting that peroxynitrite selectively supports survival of NF2 schwannoma cells." (PMID 31171721, 2019). "To date, no information is available regarding Nf2 mutations in spontaneous schwannomas occurring in the same region as OEC tumors." (PMID 31632194, 2019). "We evaluated the expression of COX2 in the yet largest cohort of 1048 vestibular schwannomas including 115 schwannomas of NF2 patients and compared the expression with demographic factors as well as tumor extension, MIB1 expression and the intake of COX2 responsive medication." (PMID 31291992, 2019). "However, the mechanism by which nitrated Hsp90 regulates NF2 schwannoma metabolism requires further study." (PMID 31171721, 2019).